GP5 (glycoprotein V platelet)
Diseases named in the same sentence as GP5 in open-access papers (continued):
Sharing a sentence is not in itself a finding about the gene and the disease.
infection (52 papers, 2005 to 2025). The state of being infected such as from the introduction of a foreign agent such as serum, vaccine, antigenic substance or organism. "The ORF5 codes PRRSV glycoprotein 5 (GP5), which has been implicated for host cell infection and as a target of NA." (PMID 36992179, 2023). "MYH9 plays a pivotal role in PRRSV infection by physically interacting with PRRSV GP5 protein through its C-terminal domain, which makes the host cells susceptible to infection." (PMID 36899670, 2023). "Integrating all observations, Abedon concluded that Spackle’s primary function is to protect the cell from damage to the cell envelope caused by gp5 that originates from virions of phages that infect after the initial infection is already under way." (PMID 32987925, 2020). "The results of challenge studies in piglets indicated that GP5-Ft could effectively resist infection from highly pathogenic PRRSV and significantly improve the survival rate of piglets." (PMID 38932282, 2024). "Finally, experimental infection of pigs with these PRRSV variants could provide evidence whether the “decoy epitope” in GP5 is required for the induction of persistent infection." (PMID 23755249, 2013). "In addition to the lysozyme responsible for ending the infection cycle, members of the T4 family generally encode a second lysozyme, usually related to the first, embedded in the central portion of key baseplate protein gp5." (PMID 21899740, 2011). "Several PRRSV structural proteins containing abundant epitopes can induce neutralizing antibodies, among which those targeting the GP5 protein show the most potent antiviral activity in preventing infection." (PMID 40572220, 2025). "In contrast, GP5-specific antibodies appeared later, between 18 and 35 dpv, aligning with studies that identified GP5-specific responses in serum samples collected four weeks post-infection using immunoblotting and ELISA." (PMID 40266122, 2025). "As a major structural protein, GP5 is the primary target of neutralizing antibodies induced by PRRSV vaccination or prior infection." (PMID 39205214, 2024). "Later in infection, the gp5 lysozyme is inactivated by the T4 spackle protein which is secreted into the periplasm." (PMID 38675830, 2024). "GP5 protein is the main protective antigen targeted by neutralizing antibody induced by PRRSV vaccination or prior infection." (PMID 36899670, 2023). "GP5 contains a T4L (T4 lysozyme)-like domain that locally digests the peptide glycan layer during infection." (PMID 36899670, 2023). "At the infection site, the outer membrane is penetrated by the T4 puncturing device composed of a trimer of gp5 attached at the end of the tail tube." (PMID 33731698, 2021). "When a pig is infected with PRRSV, epitope A rapidly elicits most of the antibodies directed to GP5 and delays the induction of NAbs against epitope B, thus affecting the ability of the pig immune system to effectively control the infection in an early stage." (PMID 34118903, 2021). "If two cysteine were exchanged in GP5, virus titers were reduced by up to 10,000-fold at 48, 72 and 96 hours post infection (p.i.)." (PMID 33891658, 2021). "Numerous neutralization studies have concentrated solely on the PRRSV GP5 protein and early in infection pigs show a strong antibody response to the GP5 protein." (PMID 33692807, 2021). "Gp5 contains a T4L-like lysozyme domain that locally digests the peptidoglycan layer upon infection." (PMID 32987925, 2020). "The T4 Spackle protein (encoded by gene 61.3) has been thought to play a role in the inhibition of gp5 lysozyme activity and, as a consequence, in making cells infected by bacteriophage T4 resistant to later infection by T4 and closely related phages." (PMID 32987925, 2020). "Viral load levels in GP5-WT vaccinated animals, increased during the infection with MN184C and reached their peak at 10DPC, which is comparable to the vector-control group." (PMID 32121277, 2020).
infection (continued). "The restoration of N-glycosylation in GP5 resulted in prolonged infection and the resistance of viruses to neutralizing antibody." (PMID 30658381, 2019). "For HPV-18 (single or multiple infection), the agreement with the GP5+/6+ LMNX assay was high, with a kappa of 0.93 (95.0% CI: 0.87–0.99)." (PMID 29454382, 2018). "The triple β-helix is reminiscent of the long β-helix in gp5 (gp5 is the tail lysozyme of phage T4, which functions as a cell-puncturing device during infection)." (PMID 28665339, 2017). "A conformational epitope of GP5 induces the production of neutralizing Ab that can be detected at the earliest four weeks after infection." (PMID 28405425, 2015). "A distinct PRRSV population was reported that emerged by one single amino acid change in the GP5 ectodomain after infection in pigs." (PMID 25885416, 2015). "Results of sequencing showed that the NE in GP4 changed during the course of the infection and that GP5 gained one potential glycosylation at N37 (DSS →NSS)." (PMID 22515169, 2012). "Although the value GP3 in this regard is intermediate between that of GP4 and GP5, it induces the highest levels of neutralizing antibody production during the early stages of infection, and it is only in the latter stages that the GP5 is more effective than GP3 and GP4 in this role." (PMID 39943200, 2025). "However, upon heterologous strain infection, the rapid rise in neutralizing antibodies within two weeks indicates a robust amnestic response against certain neutralizing epitopes including GP5." (PMID 40266122, 2025). "As more variability was noted in GP3 and ORF1ab (particularly in nsp5 and nsp9), compared to GP5, GP5-based phylogeny may overestimate the reliability of tracing the order of infection." (PMID 41334982, 2025). "Results showed that GP-1 was able to selectively lyse, although with different efficiency, 10/13 (77%) strains of K. pneumoniae ST 307 (excluding its indicator strain) and that GP-5 was able to perform a productive infection on two K. pneumoniae ST307 strains both resistant to the infection by GP-1." (PMID 39431055, 2024). "Infection of cells with the two recombinant viruses showed differential regulation of the induction of a number of innate immune and proinflammatory genes in infected cells, which was partially attributable to amino acid residue F16 in GP5(HUB2)." (PMID 37547693, 2023). "Taken together, these results demonstrate that the interaction between MARCO and GP5 may contribute to the PRRSV-induced apoptosis by which MARCO restrains PRRSV infections." (PMID 37078873, 2023). "The GP5 is also identified as a viral epitope for NA demonstrating the complexity in vaccine design and assessment for a virus where sub-neutralizing antibodies can increase infection." (PMID 36992179, 2023). "A previous study has shown that the viral GP5, a ligand protein for porcine Sn, is closely associated with PRRSV-ADE infection, implying that porcine Sn may have an essential effect on PRRSV-ADE infection." (PMID 36136686, 2022). "A previous study showed that the C-terminal end (aa 1651–1960) of MYH9 (PRA) from PAM cells could block the infection by different PRRSV strains via interaction with GP5." (PMID 35694306, 2022). "According to the infection paradigm known for planktonic cells, three gp5 lysozyme domains are liberated in the periplasm per infecting phage; thus, over time, critical damage could be done to the peptidoglycan layer just from these molecules alone." (PMID 33731698, 2021). "Moreover, interaction of Gp5 with Gp4 contributes to the precise adjustment of the timing of hole formation allowing a productive infection cycle." (PMID 30110929, 2018). "Interestingly, vaccination with GP5/M induced fever up to 41.5 °C for 1 day following challenge infection with PRRSV Olot/91 whereas mock-vaccinated pigs remained asymptomatic." (PMID 26895704, 2016).
infection (continued). "Furthermore, the involvement of GP3 and GP5 proteins in viral proliferation and viral replication during infection-induced immune responses also requires further research." (PMID 24916952, 2014). "The “decoy epitope” hypothesis makes the following predictions: Initially after infection of pigs the “decoy epitope” must be present in fully processed GP5." (PMID 23755249, 2013). "This amino acid exchange in GP5 was observed in the course of experimental infection of pigs." (PMID 23755249, 2013). "Also, different porcine cells might process GP5 differentially such that the signal peptide (including the “decoy epitope”) is removed in cells that are infected late in the course of infection." (PMID 23755249, 2013). "The “decoy epitope” hypothesis predicts that at later time points during natural infection of pigs, GP5 without “decoy epitope” is produced that causes the generation of neutralizing antibodies." (PMID 23755249, 2013). "Recombinant adenovirus pac-Ad5-34-GP5 and pac-Ad5-34-GP35 can detect GP5 and GP3-GP5 protein expression after infection of HEK293 cells were 23 kDa and 52 kDa, respectively." (PMID 39742318, 2024). "In PRRSV-infected Marc-145 cells, PRRSV GP5 was especially pulled down by the anti-Myc antibody, suggesting an interaction between PRRSV GP5 and MARCO in cases of infection." (PMID 37078873, 2023). "The specific bands of GP5 and M proteins were detected in the rPRV-NC56 infection group and the CHSCDJY-2019 infection group in the supernatant of Marc-145 cells infected with rPRV-NC56 and CHSCDJY-2019." (PMID 35308386, 2022). "PRRSV VLP was generated from infection of insect TriExTM Sf9 cells with recombinant baculoviruses expressing PRRSV M, N, E and Gp5 proteins." (PMID 28403874, 2017). "The data indicated that at 24, 48 and 72 h post-infection nsp2, GP2, GP4, GP5, M and N proteins appeared less abundant in 3-AB treated cells than the non-treated cells." (PMID 25614100, 2015). "In the present study, the MY09/MY11 and GP5+/GP6+ primers followed by DNA sequencing and type specific PCR were used to confirm the HPV genotypes and to identify the mixed infection." (PMID 24252426, 2013). "GP5, the major glycoprotein of PRRSV, is considered an important target of neutralizing antibodies, which however appear only late in infection." (PMID 23755249, 2013). "At sixty-hour post-infection, the cells were harvested to detect H-PRRSV GP5 or M protein coding genes and β-actin gene in each experimental group by real-time PCR." (PMID 22040357, 2011). "More likely, the GP5-specific antibody, BNW7p5c4, inhibits infection but does not permanently prevent it." (PMID 33692807, 2021). "Previous studies of the ectodomain of GP5 of PRRSV have detected an immunodominant epitope denominated “A” which is strongly recognized by swine sera early after infection but has no neutralizing activity." (PMID 34118903, 2021). "To investigate whether GP5 and/or M are palmitoylated, we infected MARC-145 cells with PRRSV-2 strains VR-2332 or XH-GD at a low multiplicity of infection (MOI)." (PMID 33891658, 2021). "In this study, we demonstrate that blocking of MYH9 with Mab2-5G2 significantly diminished PRRSV internalization by porcine alveolar macrophage (PAM) via interruption of direct interaction between GP5 and MYH9, and thus remarkably inhibited subsequent infection of PAMs by PRRSV-2 isolates." (PMID 31905776, 2019). "Although an infection of M. smegmatis without Gp5 results in a delay of the timing of lysis, Gp5 did not complement an Sλ defective mutant." (PMID 30110929, 2018). "Before challenge infection, vaccination with VSVΔG(GP5/M) did not induce any detectable antibody response against GP5 as measured by ELISA (not shown)." (PMID 26895704, 2016). "Following challenge infection, GP5-specific antibody responses were detected on day 7 pi in 2 out of 4 pigs, and all pigs vaccinated with VRP expressing the PRRSV proteins seroconverted to GP5 at day 11 pi." (PMID 26895704, 2016).
infection (continued). "While there is a strong antibody response directed against N and GP5 few days after infection, these antibodies do not neutralize the virus." (PMID 23755249, 2013). "The incongruity in the neutralizing role of GP5-specific antibodies may be explained by the timing of serum collection in Li and Murtaugh, which was six weeks post-infection with VR-2332, a point when neutralizing antibodies generated against GP5 might not have reached protective levels." (PMID 40266122, 2025). "Thus, apart from priming pigs for GP5-specific antibody responses after challenge infection, the VSVΔG(GP5/M) vector could not induce any seroconversion against GP5 before challenge nor any sign of protection from viremia after infection." (PMID 26895704, 2016). "Again, before challenge infection, vaccination with VRP expressing the structural proteins of PRRSV did not induce any detectable antibody response against GP5, GP4 and GP3 as measured by ELISA (not shown)." (PMID 26895704, 2016). "During infection with PRRSV, epitope A of GP5 acts as a decoy, eliciting most of the non-neutralizing antibodies directed to GP5 and delaying the induction of NAs, and making it difficult to identify the precise RBD which could induce NAs." (PMID 38956618, 2024).
cancer (19 papers, 2011 to 2025). A tumor composed of atypical neoplastic, often pleomorphic cells that invade other tissues. "We used clock-like CpG > TpG mutations (COSMIC signature SBS1) to track the cancers of both GP5 and GP12 chronologically within 95% confidence intervals (CI)." (PMID 37828555, 2023). "A total of 35 putatively oncogenic somatic variants were mapped to the GP5 cancer evolutionary tree." (PMID 37828555, 2023). "The participants who died because of cancer showed a greater abundance of GP5, 6, 16, and 37 and lesser abundance of GP4, 14, 22, 24, 27, and 33 than those who did not die because of cancer." (PMID 41106480, 2025). "Our models show strong performance in distinguishing between benign and malignant tissues, also identifying tissues with GP3, GP4, and GP5, which indicate the aggressiveness of the cancer." (PMID 40087478, 2025). "In GP5, metastatic spread from prostate to pelvic lymph nodes occurred at least five separate times, by five evolutionarily distinct cancer cell populations represented by clusters Ba and Bb and their descendants." (PMID 37828555, 2023). "Similar proportions said that GP5 was relevant (n = 7, 47%) and irrelevant (n = 6, 40%) to their cancer treatment, while 13% (n = 2) said they were unsure." (PMID 36525100, 2022). "This study suggests that GP5 is a useful, succinct measure that captures how cancer patients tolerate their treatment." (PMID 36525100, 2022). "For patients currently on treatment, the results suggest that GP5 was highly comprehensible and relevant, and it captures critical aspects of the side effects of cancer therapies." (PMID 36525100, 2022). "Because adverse effects are so varied, GP5 responses can facilitate comparisons across treatments or cancer types more easily than assessments that focus on specific types of side effects selected to suit the circumstance at hand." (PMID 35013779, 2022). "This study provides assurance that GP5 is a useful indicator of treatment tolerability, and is meaningful to people with cancer, especially once they have started treatment." (PMID 36525100, 2022). "This study suggests that GP5 may be a useful, succinct way to track whether cancer patients tolerate their treatment and may identify patients vulnerable to tolerability-associated early discontinuation." (PMID 38536173, 2024). "We hypothesized that cancer evolutionary analyses such as those shown here for GP5 and GP12 could be used to inform and improve patient treatment." (PMID 37828555, 2023). "In GP5, tumor samples 6-LCA1 and 7-LCA2 contained the largest fraction of cancer cells harboring solely truncal (most recent common ancestor, MRCA) mutations, implicating the left posterior mid-apex region as the putative site of origin of the cancer." (PMID 37828555, 2023). "For this reason, GP5 has already been employed in multiple trials evaluating cancer treatments." (PMID 35031830, 2022). "Given its level of generality, GP5 may be a useful complement to the PRO-CTCAE in cancer trials, helping to evaluate the overall burden of treatment-related toxicity." (PMID 35031830, 2022). "GP5 responses were distributed similarly across most cancer sites." (PMID 35031830, 2022). "In patient GP5, CDK12 inactivation was among the first mutations, leading to a PrCa tandem duplicator phenotype and initiating the cancer around age 50, followed by rapid cancer evolution after age 57, and metastasis around age 59, 5 years prior to prostatectomy." (PMID 37828555, 2023). "DNA was extracted from the confirmed cancer biopsies, followed by PCR using MY09/GP5+ /6+ primers to detect the presence of HPV and specific primers for the amplification of L1 gene and LCR." (PMID 38037052, 2023). "The detection of HPV types in cancer is commonly done by different PCR assays which utilize various universal primers including MY09/MY11, GP5/GP6, GP5+/GP6+, CP65/CP70, CP66/CP69, and SPF1/SPF2 designed during 1990s or earlier." (PMID 26766963, 2016).
cancer (continued). "For GP5, CDK12 inactivation and gains of AKT1, GSK3B, PIK3CA, CCND1, and MDM2 were identified as the top truncal druggable targets that would be most likely to obtain a durable response due to their presence in all cancer cells." (PMID 37828555, 2023). "Similarly, when assessing convergent validity between GP5 responses and cancer site, moderate negative correlations were revealed for most cancer sites." (PMID 35031830, 2022). "DNA methylation alterations in UNC13A, SP9, GP5, C1QL3, SP8, and VWC2 have not been previously reported in cancer." (PMID 26380585, 2015).